ATPAF2 (ATP synthase mitochondrial F1 complex assembly factor 2)
Description:
Plays a role in the assembly of the F1 component of the mitochondrial ATP synthase (ATPase).
Synonyms: ATP12; LP3663; Atp12p; MGC29736; MC5DN1
Tractability: Antibody: UniProt places it where antibodies can reach, with high confidence. PROTAC: its protein half-life has been measured.
Gene: Protein-coding gene on chromosome 17 (17,977,409 to 18,039,209, reverse strand). Ensembl gene ENSG00000171953.
Subcellular location: Mitochondrion inner membrane
Subcellular location (Human Protein Atlas): Cytosol
Gene Ontology:
Molecular function: protein binding; protein folding chaperone
Biological process: mitochondrial proton-transporting ATP synthase complex assembly; proton-transporting ATP synthase complex assembly; protein folding
Cellular component: mitochondrial inner membrane; mitochondrion; nuclear speck
Genetic constraint (gnomAD): Loss-of-function variants: 30 observed, 37 expected, observed/expected ratio (o/e) 0.81, 90% interval 0.61 to 1.1. The upper end of that interval is the gene's LOEUF score, 1.1, which puts it in group 4 of 6, group 1 being the genes least tolerant of losing a copy. Missense variants: 320 observed, 387.44 expected, observed/expected ratio (o/e) 0.83, 90% interval 0.75 to 0.91. Synonymous variants: 138 observed, 160.13 expected, observed/expected ratio (o/e) 0.86, 90% interval 0.75 to 0.99.
Gene-disease validity (ClinGen):
ClinGen rates the evidence that ATPAF2 causes each of these diseases.
mitochondrial disease (autosomal recessive): Limited.
Homologues: Orthologues: chimpanzee ATPAF2 (99% identical), macaque ATPAF2 (98% identical), guinea pig ATPAF2 (91% identical), dog ATPAF2 (89% identical), pig ATPAF2 (88% identical), mouse Atpaf2 (87% identical), rat Atpaf2 (84% identical), tropical clawed frog atpaf2 (68% identical), zebrafish atpaf2 (62% identical), Drosophila melanogaster l(2)k14505 (41% identical), Caenorhabditis elegans Y116A8C.27 (26% identical).
Diseases named in the same sentence as ATPAF2 in open-access papers:
ATPAF2 is named in the same sentence as 6 diseases in open-access papers, as found by Europe PMC text mining. Sharing a sentence is not in itself a finding about the gene and the disease. The quoted sentences say what the papers report.
mitochondrial disease (2 papers, 2017 to 2021). "In two replicates, we observed only a single high-abundance endogenous binding partner: ATPAF2, a known assembly factor the F1 ATP synthase that is mutated in a human mitochondrial disease." (PMID 28719601, 2017). "Until now, only three of the sixteen nucleus-encoded CV subunits and three assembly factors (e.g., ATPAF2; ATP12 and TMEM70) have been associated with mitochondrial disease." (PMID 34361091, 2021).
neurological diseases (2 papers, 2021 to 2022). "The regions of the 3 CNVs are located in chromosome Xp22.31, 15q11.2–13.1 and 17p11.2, and harbored genes associated with neurological diseases including GABRB3, UBE3A, MAGEL2, RAI1, ALDH3A2, ATPAF2 according to the database of Online Mendelian Inheritance in Man (OMIM)." (PMID 33753861, 2021).
ATPAF2 also shares sentences with these, for which no sentence is quoted: allergic respiratory disease (1 paper); mental disorder (1); metabolic disease (1); status epilepticus (1).